Y_RNA (Y RNA )
Gene: Miscellaneous RNA gene on chromosome 3 (196,202,349 to 196,202,453, forward strand). Ensembl gene ENSG00000222335.
Homologues: Orthologues: chimpanzee Y_RNA (96% identical), macaque Y_RNA (94% identical). Paralogues in human: Y_RNA (80% identical), RNY1 (79% identical), Y_RNA (79% identical), RNY1P11 (78% identical), Y_RNA (78% identical), Y_RNA (77% identical), Y_RNA (76% identical), RNY1P10 (75% identical), RNY1P13 (75% identical), RNY1P3 (75% identical), RNY1P7 (75% identical), Y_RNA (75% identical), and 94 more.